SFRP4 (secreted frizzled related protein 4)
Diseases named in the same sentence as SFRP4 in open-access papers (continued):
Sharing a sentence is not in itself a finding about the gene and the disease.
cystic kidney disease (1 paper, 2020). A congenital or acquired kidney disorder characterized by the presence of renal cysts. "Elevated levels of sFRP4 expression have also been observed in human patients of ADPKD and animal models of cystic kidney disease, including in NPHP, highlighting a relationship between the induction of sFRP4 expression and renal cystogenesis." (PMID 32365994, 2020).
dementia (1 paper, 2026). Loss of intellectual abilities interfering with an individual's social and occupational functions. "Two proteins, sFRP4 and MEPE, were linked to reduced Brain Age, with sFRP4 also being protective against dementia." (PMID 41555457, 2026).
diabetic cardiomyopathy (1 paper, 2022). Diabetic cardiomyopathy is a disorder of the heart muscle in people with diabetes. "As mentioned in the introduction, bioinformatics analysis found that SFRP4 was upregulated in diabetic cardiomyopathy." (PMID 35290144, 2022). "On the basis of bioinformatics analysis, SFRP4 is also up-regulated in diabetic cardiomyopathy." (PMID 35290144, 2022). "Therefore, in this study, we aimed to identify the role and mechanism of SFRP4 in diabetic cardiomyopathy." (PMID 35290144, 2022). "Overall, our study elucidated that downregulation of SFRP4 attenuated cardiomyocyte injury in H/R models and regulated the activation of the P13 K/AKT signaling pathway through PTPN12, which possibly provides a novel therapeutic target for patients with diabetic cardiomyopathy." (PMID 35290144, 2022).
diffuse astrocytoma (1 paper, 2024). A low-grade (WHO grade II) astrocytic neoplasm. "Therefore, the present study aims to explore the SFRP4 promoter methylation status and its consequence on protein levels in diffuse astrocytoma grade 2–4." (PMID 38993819, 2024).
Dysmenorrhea (1 paper, 2024). Pain during menstruation that interferes with daily activities. "The relationship between dysmenorrhea and expression of COX-2, WBP2, IFITM3, and SFRP4." (PMID 38239300, 2024).
endometrioid carcinomas (1 paper, 2018). "In our series, hypermethylation of the Wnt antagonists (DKK1, DKK2, SFRP1, SFRP4, SFRP5, and WIF1) were observed with a significant prevalence in mucinous and endometrioid carcinomas." (PMID 29882921, 2018).
endometriosis (1 paper, 2012). The growth of functional endometrial tissue in anatomic sites outside the uterine body. "Indeed, we found a decline in cumulative SFRP4 expression from tubal epithelium, benign tissues (including ovarian surface epithelium and inclusion cysts), endometriosis to borderline tumors and cancers, again in consistency with the trend we found by RT-qPCR in cell lines." (PMID 22363760, 2012).
gallstones (1 paper, 2024). Solid crystalline precipitates in the biliary tract, usually formed in the gallbladder, resulting in the condition of cholelithiasis. "The results indicated that AC004692.4, HECW1-IT1, SFRP4, and COMP were significantly higher expressed in gallstone samples, whereas LINC01564, SLC26A3, RP1-27K12.2, and GSTA2 were markedly lower expressed in gallstone samples compared to control samples." (PMID 38808330, 2024). "Furthermore, using RT-qPCR, we observed significant upregulation of AC004692.4, HECW1-IT1, SFRP4, and COMP, while LINC01564, SLC26A3, RP1-27K12.2, and GSTA2 exhibited marked downregulation in gallstone samples." (PMID 38808330, 2024).
Glucose intolerance (1 paper, 2017). Glucose intolerance (GI) can be defined as dysglycemia that comprises both prediabetes and diabetes. "SFRP4 treatment resulted in a decrease in insulin secretion and glucose intolerance, while silencing of SFRP4 led to glucose-stimulated insulin release." (PMID 29037197, 2017).
head and neck squamous cell carcinoma (1 paper, 2024). A squamous cell carcinoma that arises from any of the following anatomic sites: lip and oral cavity, nasal cavity, paranasal sinuses, pharynx, larynx, and salivary glands. "Interestingly, a recent study demonstrated that an immune-related gene prognostic index constructed using SFRP4, CPXM1, and COL5A was associated with better survival and better responses to immune checkpoint inhibitor therapy for head and neck squamous cell carcinoma." (PMID 38664626, 2024).
hepatocellular carcinoma (1 paper, 2024). A malignant tumor that arises from hepatocytes. "For example, SFRP4 inhibits aggressive traits of hepatocellular carcinoma (HCC) cells by reducing β-catenin levels, thereby blocking the Wnt/β-catenin signaling pathway." (PMID 38426532, 2024).
hyperphosphatemia (1 paper, 2017). Abnormally high level of phosphate in the blood. "SFRP4 has a phosphaturic action similar to that of FGF-23,46 and its downregulation may be relevant to the persistent hyperphosphatemia seen in this patient." (PMID 28326223, 2017).
hypophosphatemia (1 paper, 2023). Lower than normal levels of phosphates in the circulating blood. "Overexpression of MEPE and SFRP-4 can lead to abnormal renal phosphate metabolism and bone mineralization, causing hypophosphatemia and increased renal phosphate excretion." (PMID 38116308, 2023).
infertile (1 paper, 2023). "SFRP4 has also been identified as significantly downregulated in uterine lavage samples of infertile women, and this downregulation may affect the proper endometrial development necessary for successful implantation." (PMID 36986136, 2023).
ischemia (1 paper, 2025). A hypoperfusion of the BLOOD through an organ or tissue caused by a PATHOLOGIC CONSTRICTION or obstruction of its BLOOD VESSELS, or an absence of BLOOD CIRCULATION. "Some studies have demonstrated that knocking out SFRP4 can appreciably mitigate cardiac damage after ischemia-reperfusion injury." (PMID 40066352, 2025).
leiomyoma (1 paper, 2017). A well-circumscribed benign smooth muscle neoplasm characterized by the presence of spindle cells with cigar-shaped nuclei, interlacing fascicles, and a whorled pattern. "Another key question that arises from our work is how inhibition of high levels of sFRP4 expression in leiomyomas by activation of the PR contributes to tumor growth during the luteal menstrual phase." (PMID 28637297, 2017). "Knockdown of sFRP4 inhibited proliferation and apoptosis in primary cultures of both myometrium and leiomyoma." (PMID 28637297, 2017). "Additional work is needed to elucidate how the overexpression of sFRP4 contributes to the ability of progesterone to promote leiomyoma growth and determine how its distinct pattern of regulation contributes to uterine smooth muscle tumorigenesis." (PMID 28637297, 2017). "Our analyses indicated that among genes differentially expressed in leiomyomas, the PR is functionally linked to both ESR1 and sFRP4." (PMID 28637297, 2017). "Semiquantitative assessment of sFRP4 expression confirmed that sFRP4 is robustly overexpressed in specimens of leiomyomas collected from the proliferative and luteal phase of the menstrual cycle (n = 20 each group; data not shown)." (PMID 28637297, 2017). "In contrast, our data clearly demonstrate that knockdown of sFRP4 inhibits the proliferation of leiomyoma cells in vitro." (PMID 28637297, 2017). "Overexpression of sFRP4 is a robust, progesterone-regulated feature of leiomyomas that increases smooth muscle proliferation." (PMID 28637297, 2017). "Although the mean expression score for sFRP4 in luteal leiomyomas was lower than in proliferative phase specimens, this difference was not statistically significant." (PMID 28637297, 2017). "We also evaluated sFRP4 expression by immunohistochemistry by using a tissue microarray constructed from a third set of matched leiomyoma and myometrial specimens." (PMID 28637297, 2017). "Knockdown of sFRP4 resulted in decreased rates of proliferation and apoptosis in primary cultures of both leiomyoma and myometrium." (PMID 28637297, 2017). "Progesterone preferentially inhibited sFRP4 expression and secretion in leiomyoma cultures in a dose-dependent manner sensitized by estradiol." (PMID 28637297, 2017). "Studying patterns of gene expression that vary by menstrual phase, we found that overexpression of sFRP4 is a progesterone-regulated feature of leiomyomas that regulates smooth muscle proliferation." (PMID 28637297, 2017). "Long-term efforts to better understand these mechanisms will help determine whether or how small-molecule inhibitors for sFRP4 could be used to control symptoms of leiomyomas." (PMID 28637297, 2017). "Given that levels of sFRP4 transcript were not significantly affected by the application of estradiol to primary cultures of myometrium or leiomyoma in vitro, it is possible that the ability of estradiol to inhibit sFRP4 expression ultimately relies on a posttranscriptional mechanism." (PMID 28637297, 2017). "It is possible that, when removed from this context, leiomyoma cells respond differently to sFRP4." (PMID 28637297, 2017). "In our initial whole genome transcriptional profiling, sFRP4 expression was both 2.6 times greater in fibroids as compared with myometrium (P < 0.01) and 2.5 times greater in leiomyomas collected in the proliferative phase than specimens collected during the luteal phase (P < 0.01)." (PMID 28637297, 2017). "Additional work will be needed to confirm that sFRP4 promotes leiomyoma growth in vivo." (PMID 28637297, 2017). "However, low doses of estradiol did potentiate progesterone’s ability to inhibit sFRP4 expression in primary leiomyoma cultures." (PMID 28637297, 2017). "Therefore, we also sought to determine whether primary cultures of myometrium and leiomyomas secrete sFRP4 into their local environment." (PMID 28637297, 2017).
leiomyoma (continued). "No qualitative differences patterns of sFRP4 immunoreactivity were observed when proliferative and luteal phase specimens of myometrium and leiomyomas were compared (data not shown)." (PMID 28637297, 2017). "Evaluation of genomic DNA immunoprecipitated by a high-fidelity antibody specific to the PR demonstrated clear enrichment for sFRP4 promoter in specimens of both myometrium and leiomyoma as compared with control input DNA precipitated with nonspecific immunoglobulins." (PMID 28637297, 2017). "At present, the mechanisms driving the high levels of sFRP4 expression in leiomyomas are not known." (PMID 28637297, 2017). "Of note, levels of sFRP4 increased with confluency, regardless of whether that culture had been obtained from a specimen of myometrium or leiomyoma (data not shown)." (PMID 28637297, 2017).
metabolic syndrome (1 paper, 2014). A cluster of metabolic risk factors for CARDIOVASCULAR DISEASES and TYPE 2 DIABETES MELLITUS. "We not only observe an association of higher SFRP4 concentrations with T2DM but also with the metabolic syndrome." (PMID 25408147, 2014).
mucinous carcinomas (1 paper, 2018). "There are six genes (MAL, MYOD1, OSMR, SEPTIN9, SFRP1, and SFRP4) for which hypermethylation is observed almost exclusively or preferentially in mucinous carcinomas." (PMID 29882921, 2018).
mucinous ovarian cancer (1 paper, 2012). An invasive malignant neoplasm that arises from the ovary and is characterized by the presence of malignant epithelial cells that contain intracytoplasmic mucin and may resemble the epithelial cells of the endocervix or gastrointestinal tract. "We performed sFRP4 and β-catenin IHC on primary mucinous ovarian cancer biopsies in tissue microarrays (TMAs) comprising 104 primary mucinous ovarian tumours." (PMID 23039795, 2012).
mucinous ovarian tumours (1 paper, 2012). "The primary mucinous ovarian tumours were classified into three sub-types; namely benign, borderline, and adenocarcinomas, and the proportion of sFRP4 and β-catenin was quantified for each." (PMID 23039795, 2012).
mucinous tumours (1 paper, 2012). "In contrast to their sFRP4 expression, adenocarcinomas expressed significantly higher levels of β-catenin, indicating an inverse relationship between β-catenin and sFRP4 expression in benign and malignant mucinous tumours." (PMID 23039795, 2012).
Myocardial fibrosis (1 paper, 2024). "Regarding the evident expression of SFRP4 in cardiac fibroblasts of failed hearts, we mechanically speculated that elevated SFRP4 affects myocardial fibrosis and remodeling post-HF." (PMID 38397416, 2024).
myocardial hypertrophy (1 paper, 2024). "Furthermore, SFRP4 functions as a high-affinity protein capable of binding to Wnt ligands, thereby playing a crucial role in various pathological processes associated with HF, including myocardial hypertrophy and fibrosis, through the modulation of Wnt pathway activity." (PMID 39062507, 2024).
oropharyngeal cancers (1 paper, 2015). Carcinoma, predominantly squamous cell, arising from the epithelial cells of the oropharynx. "In this regard, frequent hypermethylation of the negative regulators of this pathway (DKK-3, RUNX3, SFRP1, SFRP2, SFRP4, SFRP5, and WIF1) was observed in oral and oropharyngeal cancers." (PMID 25487617, 2015).
polyp (1 paper, 2008). A usually exophytic mass attached to the underlying tissue by a broad base or a thin stalk. "Similarly, CGI methylation of SFRP4, SFRP5 and WIF1 correctly identified 61.5% of polyp patients and 78.9% of neoplasia-free subjects (P=0.0167)." (PMID 18542073, 2008).
postmenopausal osteoporosis (1 paper, 2023). Metabolic disorder associated with fractures of the femoral neck, vertebrae, and distal forearm. "SFRP4 is unlikely to be involved in postmenopausal osteoporosis as cortical and trabecular bone losses following ovariectomy in adult mice was unaffected by Sfrp4 KO." (PMID 36808149, 2023).
preeclampsia (1 paper, 2022). Preeclampsia is a hypertensive disorder of pregnancy that is characterized by new-onset hypertension with proteinuria presenting after 20 weeks of gestation, and depending on mild or severe forms may initially present with severe headache, visual disturbances, and hyperreflexia. "Some genes are noted to play key roles in preeclampsia, including LPAR4/5, CRLR, NPY, TACR1/2, and SFRP4/5, whose functions generally relate to angiogenesis and vasodilation or vasoconstriction." (PMID 35269385, 2022). "SFRP4 and SFRP5 are observed to be upregulated in patients with severe preeclampsia." (PMID 35269385, 2022).
pterygium (1 paper, 2022). A wedge-shaped fibrovascular lesion arising from the bulbar conjunctiva and extending to the cornea. "We finally chose night genes to verify their expression levels, including the other two genes (SFRP2 and SFRP4) involved in Wnt signaling; Their expression levels were significantly different between pterygium and conjunctiva." (PMID 36187094, 2022).
renal cell carcinoma (1 paper, 2018). "A previous study compared the genotypes distribution between renal cell carcinoma (RCC) patients and controls showed that SFRP4 rs1802074 polymorphism was related to RCC susceptibility." (PMID 29666772, 2018).
renal failure (1 paper, 2023). "SFRP4 serum concentrations were elevated and correlated with the degree of renal failure." (PMID 38027263, 2023).
skin aging (1 paper, 2022). The gradual irreversible changes in structure of skin that occur as a result of the passage of time.. "Decreases in collagen III with aging have been also reported previously suggesting that knockdown of SFRP4 has a protective effect on skin aging via collagen III increase and SASP suppression." (PMID 36084952, 2022). "We investigated the possibility that the in vivo inhibition of SFRP4 might inhibit SASP-induced skin aging in mice." (PMID 36084952, 2022).
skin atrophy (1 paper, 2022). The degeneration and thinning of the epidermis and dermis. "Since the skin is essentially atrophic in aging mice and this phenotype of skin atrophy has been repeatedly reported as comparable in humans, we focused on the effects of SFRP4 knockdown on aging mouse skin." (PMID 36084952, 2022).
Uterine leiomyoma (1 paper, 2017). The presence of a leiomyoma of the uterus. "Our observations clearly demonstrate that overexpression of sFRP4 is a robust, progesterone-regulated feature of uterine leiomyomas." (PMID 28637297, 2017). "In part, the mechanisms by which the tight regulation of sFRP4 expression in uterine leiomyomas promotes their growth may depend on the subpopulation of cells within the tumor complex on which sFRP4 exerts its impact." (PMID 28637297, 2017).